RN7SL807P (RNA, 7SL, cytoplasmic 807, pseudogene)
Gene: Miscellaneous RNA gene on chromosome 2 (223,248,498 to 223,248,794, reverse strand). Ensembl gene ENSG00000243125.
Homologues: Orthologues: chimpanzee Metazoa_SRP (99% identical), macaque Metazoa_SRP (88% identical). Paralogues in human: RN7SL1 (81% identical), RN7SL2 (80% identical), RN7SL3 (79% identical), RN7SL322P (78% identical), RN7SL44P (78% identical), RN7SL451P (78% identical), RN7SL408P (78% identical), RN7SL664P (78% identical), RN7SL679P (77% identical), RN7SL296P (77% identical), RN7SL42P (77% identical), RN7SL45P (77% identical), and 698 more.